WNT6 (Wnt family member 6)
Diseases named in the same sentence as WNT6 in open-access papers (continued):
Sharing a sentence is not in itself a finding about the gene and the disease.
renal fibrosis (3 papers, 2016 to 2021). A final common manifestation of a wide variety of chronic kidney diseases characterized by glomerulosclerosis and tubulointerstitial fibrosis. "Moreover, the ability of WNT6 expression maintain the integrity of the epithelium is also an important theoretical basis for it to become a therapeutic target for renal fibrosis." (PMID 33425886, 2020). "Thus, WNT6 has a protective effect on the kidneys and prevents renal fibrosis by regulating epithelial fate." (PMID 33425886, 2020). "Although the function of Wnt11 and Wnt6 in liver fibrosis was unknown, Wnt11 was shown to enhance the expression of mesenchymal markers, such as Zeb1, Snail1, Pai1 and α-SMA, in response to the TGF-β signaling in renal fibrosis, and Wnt6 was reported to be downregulated during renal fibrogenesis." (PMID 27322257, 2016).
Rett syndrome (3 papers, 2020). A severe neurodevelopmental disorder affecting the central nervous system. "In addition, overexpression of Wnt6 ameliorates synaptic and behavioral deficits in mice model of Rett syndrome (Hsu, Ma, Liu, Tai, & Lee, 2020)." (PMID 32856797, 2020).
Alzheimer disease (2 papers, 2014 to 2024). A progressive, neurodegenerative disease characterized by loss of function and death of nerve cells in several areas of the brain leading to loss of cognitive function such as memory and language. "These categories include WNT (WNT1, WNT3A, WNT6, AXIN2, TNF2, MMP7), Alzheimer disease presenilin (WNT1, WNT3A, WNT6, MMP7), cadherin (WNT1, WNT3A, WNT6) and Notch (LFNG, HES1) signaling pathways." (PMID 38928376, 2024).
chronic lymphocytic leukaemia (2 papers, 2020 to 2021). "Wnt members, including Wnt3, Wnt4, Wnt5B, Wnt6, Wnt7B, Wnt9A, Wnt10A, Wnt14 and Wnt16, are highly expressed in chronic lymphocytic leukaemia B cells." (PMID 33417298, 2021).
colorectal adenoma (2 papers, 2015 to 2016). An adenoma that arises from the colon or rectum. "Dysregulation of Wnt6 has been shown to be related to carcinogenesis: single nucleotide polymorphisms (SNPs) in the Wnt6 gene could be associated with enhanced risk for developing colorectal adenomas." (PMID 28082976, 2016).
osteosarcoma (2 papers, 2021 to 2022). A usually aggressive malignant bone-forming mesenchymal neoplasm, predominantly affecting adolescents and young adults. "Their results demonstrate how the detection of peripheral WNT6 mRNA presents an ROC curve with an area under the curve (AUC) to differentiate osteosarcoma from other entities of 0.854 with a sensitivity of 88.4% and a specificity of 77.8%." (PMID 36499267, 2022). "The high expression level of WNT6 in primary osteosarcoma is mainly due to the low DNA methylation level of WNT6, while the DNA methylation of WNT6 shows a negative correlation with the prognosis of children with osteosarcoma." (PMID 34957096, 2021).
acute lymphoblastic leukemia (1 paper, 2020). Leukemia with an acute onset, characterized by the presence of lymphoblasts in the bone marrow and the peripheral blood. "Other Wnts such as Wnt4, Wnt5B, Wnt6, Wnt7B, Wnt9A, Wnt10A, Wnt14, and Wnt16 are robustly expressed in CLL B-cells and acute lymphoblastic leukemia (ALL) cells, whereas these can be scarcely detected in normal pre-B cells." (PMID 33126517, 2020).
bone sarcoma (1 paper, 2015). A sarcoma that arises from the bone. "In contrast, among noncanonical Wnt ligands, the expression of Wnt5a, Wnt5b and Wnt16 was either decreased or lost in bone sarcoma cells; however, Wnt6, Wnt7b, and Wnt11 were remarkably increased in bone sarcoma cells." (PMID 25999350, 2015). "Clearly, further studies are needed to determine the primary function of Wnt6, Wnt7b and Wnt11 in bone sarcomas." (PMID 25999350, 2015). "In contrast, the noncanonical Wnt6, Wnt7b, and Wnt11 were significantly increased in bone sarcoma cells." (PMID 25999350, 2015).
cocaine addiction (1 paper, 2020). "Twelve DEGs (Myct1, Gm21860, Ninj2, Fam183b, Lars2, Alkbh1, Fgf5, Frmd7, Tm6sf2, Wnt6, Batf3, and Clca1) were found to be regulated inversely among the overlap genes, which may be possible targets of RPA to disrupt the cocaine addiction process." (PMID 32489401, 2020).
colitis (1 paper, 2022). Inflammation of the colon. "Western blot analysis of the colon samples for Wnt6 and Wnt10a expression confirmed a reduction in these two proteins in colitis mice, which was rescued by BBR." (PMID 36528592, 2022).
colon cancer (1 paper, 2023). "Wnt6 is also a known contributor to tumorigenesis and the development of colon cancer via its effects on cell proliferation, apoptosis, and migration." (PMID 36833237, 2023).
heart attack (1 paper, 2022). "Wnt6 and sFRP1 molecules not only regulate normal embryonic heart development, but also regulate repair and regeneration after heart muscle injury in animal models of heart attack (myocardial infarction)." (PMID 35942683, 2022).
liver fibrosis (1 paper, 2016). "In the current study, the Hh-related genes, including Bmp4, Gas1, Gli3, Hhip, Ihh, Prkacb, Stk36, Wnt6, Wnt10b, Wnt9a and Wnt11, were dysregulated in our murine model of CCl4-induced liver fibrosis." (PMID 27322257, 2016).
meningioma (1 paper, 2020). A generally slow growing tumor attached to the dura mater. "Mutations in POLR2A lead to dysregulation of key meningeal identity genes ranging from wingless-type MMTV integration site family, member 6 (WNT6) to alpha prolamins (ZIC1) and are found in approximately 6% of meningiomas." (PMID 33346248, 2020).
Mycobacterium infection (1 paper, 2019). Infections with bacteria of the genus Mycobacterium. "Mycobacterium infection induces Wnt6 expression and promotes anti-inflammatory phenotype of macrophages through Arginase-1 expression." (PMID 31736969, 2019).
Obesity (1 paper, 2021). Accumulation of substantial excess body fat. "Thus, induction of Wnt6 could ameliorate metabolic abnormalities such as obesity and T2DM." (PMID 34042263, 2021).
osteoporosis (1 paper, 2020). A condition of reduced bone mass, with decreased cortical thickness and a decrease in the number and size of the trabeculae of cancellous bone (but normal chemical composition), resulting in increased fracture incidence. "For example, Wnt6 is expressed during long bone development, whereas the expression level of Wnt10a was also revealed downregulated in Runx2 knockout mice, as well as bone marrow MSCs isolated from ovariectomy-induced osteoporosis mice." (PMID 32829178, 2020).
preeclampsia (1 paper, 2024). Preeclampsia is a hypertensive disorder of pregnancy that is characterized by new-onset hypertension with proteinuria presenting after 20 weeks of gestation, and depending on mild or severe forms may initially present with severe headache, visual disturbances, and hyperreflexia. "Additionally, increased SIGLEC6 in trophoblast cells impairs vascular endothelial cell function by down-regulating Wnt6/β-catenin signal transduction in preeclampsia." (PMID 38894741, 2024).
pulmonary fibrosis (1 paper, 2020). Chronic progressive interstitial lung disorder characterized by the replacement of the lung tissue by connective tissue, leading to progressive dyspnea, respiratory failure, or right heart failure. "It was noteworthy that several associated genes (such as TGF‐β, MMP9 and Wnt6) were up‐regulated in pulmonary fibrosis model, which coincided with previous studies." (PMID 32548952, 2020).
Sepsis (1 paper, 2019). Sepsis is defined as life-threatening organ dysfunction caused by a dysregulated host response to infection. "In fact, cumulative evidence supports the role of the Wnt pathway in the regulation of the macrophage-mediated inflammatory response in sepsis, in which Wnt3a and Wnt6 reduce TNFα secretion and promote the differentiation towards an M2 anti-inflammatory phenotype attenuating the immune response." (PMID 31665078, 2019).
vitiligo (1 paper, 2020). Generalized well circumscribed patches of leukoderma that are generally distributed over symmetric body locations and is due to autoimmune destruction of melanocytes. "WNT6 being one of the enriched genes has been previously reported for vitiligo therapeutics and wound healing through melanocyte stem cell differentiation." (PMID 32509450, 2020). "Therefore, other differential genes which were enriched along with WNT6, DCT, TYR, EDNRB and TYRP1 by GO could provide more insights on vitiligo prognosis." (PMID 32509450, 2020).
tumor (18 papers, 2014 to 2025). "Additionally, Wnt6 expression is linked to advanced tumor stages, lymph node involvement, and a reduced response to ECF chemotherapy (epirubicin, cisplatin, and 5-fluorouracil)." (PMID 40943055, 2025). "Immunohistochemical staining of Wnt6 in human skin, primary tumor tissue and metastatic tissue revealed strong staining, which therefore corresponded to our results on the mRNA expression levels detected via qRT‒PCR." (PMID 38388496, 2024). "In order to further prove that NE can regulate the expression level of WNT7A, we detected the expression levels of Wnt1, Wnt2, Wnt3a, Wnt4, Wnt5a, Wnt6, Wnt7a and Wnt10a in tumour tissues of anti-PD-1 mAb + Vehicle and NE + anti-PD-1 mAb + Vehicle groups." (PMID 36646807, 2023). "The acceleration of tumor progression by WNT6 is not only reflected in the basic molecular mechanisms, but also in the clinical prognosis." (PMID 33425886, 2020). "WNT6 promotes chemoresistance in various cancer cells, as it is up-regulated by chemotherapeutics, thereby enhancing tumor resistance, aggressiveness and progression." (PMID 33473258, 2020). "This indicates that WNT6 protein expression can regulate apoptosis-regulated genes to inhibit apoptosis and promotes tumor development." (PMID 33425886, 2020). "By contrast, the overexpression of both WNT6 and Cav1 decreases cell death, indicating that Cav1 activates WNT6 to prevent tumor cell apoptosis, and induces chemoresistance through the β-catenin-dependent WNT pathway." (PMID 33425886, 2020). "The expression levels of Wnt2B, Wnt3A, Wnt6, Wnt8B and Wnt10B were significantly higher in primary liver tumor tissues than which in adjacent non-tumor tissues." (PMID 30814912, 2019). "Consistent with its anti-tumor effects, PD407824 downregulated Wnt6 and Wnt7b, two genes linked to tumor progression." (PMID 29507695, 2018). "WNT6 and WNT11 encode Wnt ligands that have potential tumor-promoting roles even in CRCs with APC mutations and that have the capability to signal to the stromal components to modulate the tumor microenvironment." (PMID 24651522, 2014). "Moreover, Wnt6 was found in the plasma of tumor cells, with nearly 50% of patients exhibiting high Wnt6 expression." (PMID 40943055, 2025). "Interestingly, most of the CpG sites are more frequently methylated in LGG than GBM patients (19 out of 28), suggesting that WNT6 locus may be globally hypomethylated during tumor progression." (PMID 31923345, 2020). "EC is characterized by elevated expression of multiple Wnt ligands (notably Wnt2, Wnt3, Wnt5A, and Wnt6) and FZD receptors, often correlating with poorer differentiation, higher potential of tumor invasion, and shorter survival." (PMID 40943055, 2025). "Consistent with low WNT signaling in RevCSCs, BLM tumor stem cells had decreased expression of WNT/stemness-related genes compared to Min tumors such as Axin2, Id2, Sox4, Wnt6, Wnt10a, Id3, Prox1, and Id1." (PMID 38893159, 2024). "In summary, WNT6 accelerates the development of GBM in various aspects; therefore, it is a critical biomarker of tumor recurrence." (PMID 33425886, 2020). "Many in vitro and in vivo studies show that in different tumor types, such as colorectal, lung, breast, or hepatocellular cancer, specific WNTs, including WNT1, WNT2, WNT3A, WNT6, WNT8B, WNT7B, and WNT16B, can activate canonical Wnt signaling and support tumor proliferation." (PMID 36982422, 2023).
tumor (continued). "PLAGL2 combines with the WNT6 promoter and activates the β-catenin-dependent WNT signaling pathway, thereby stimulating various downstream target genes (such as MMP7, CCND1) and promoting tumor development." (PMID 33425886, 2020). "Remarkably, for the very first time, we could show that PTSMT are characterized by WNT6/WNT10A regulation while all other tumor entities under investigation showed almost no expression of these two factors." (PMID 29881541, 2018). "Moreover, WNT6 increases the capacity of GBM cells to form neurospheres and the frequency of neurosphere formation (upon culturing under GSC conditions), functionally indicating that WNT6 positively correlates with the self-renewal capacity of tumor stem cells." (PMID 33425886, 2020).
cancer (17 papers, 2012 to 2026). A tumor composed of atypical neoplastic, often pleomorphic cells that invade other tissues. "RCC tissues that successfully generated organoids highly expressed genes associated with stemness (WNT6/11, FZD8/9 and JAG2), cell matrix (MMP2, COL1A1), fatty metabolism (ACOT2, LIPE) and cancer development (TGFB1, SMAD6/7, EGF and FGF1)." (PMID 35802820, 2022). "Wnt6 is a gene in the Wnt/β-catenin pathway that can be activated through Plagl2 and can promote cancer development in CRC." (PMID 33396408, 2020). "Additionally, in primary cancer, WNT6 suppresses rapid proliferation in the early stages of tumorigenesis, and its expression can be silenced." (PMID 33425886, 2020). "Beyond this, the pathway in cancer revealed that most of the genes are relative to WNT pathway (WNT7B, WNT6, WNT10B, FZD6, FZD8, and LPAR5), and among these, WNT7B, WNT10B, FZD6, FZD8, and LPAR5 belonged to the classical WNT pathway." (PMID 34122668, 2021). "In-depth analysis of epithelial cells identified H19 + myoepithelial cells (H19 + myoEpC) as the dominant malignant subpopulation, enriched in ACCB compared to other cancers and characterized by high expression of oncogenic pathways and ligands such as LAMB1 and WNT6." (PMID 41761191, 2026). "Our findings suggest that TQ modulates Wnt signaling by altering the expression of its core components (WNT7B and WNT6) and regulators (PDE2A and Sema3C), thereby potentially downregulating this oncogenic pathway and contributing to its anti-cancer mechanism in vitro." (PMID 39874307, 2025). "WNT6 and HOXA9 co‐expression in all cancer types with available RNAseq data in TCGA." (PMID 31923345, 2020).
infection (3 papers, 2020 to 2024). The state of being infected such as from the introduction of a foreign agent such as serum, vaccine, antigenic substance or organism. "Infection of the mouse lung with M. tuberculosis leads to an increase in the level of wnt6 mRNA compared to other wnt genes." (PMID 33425886, 2020). "Moreover, the infection of human monocyte-derived macrophages with M. tuberculosis H37Rv increases wnt6 mRNA expression, suggesting the regulation of a similar WNT homolog in human macrophages." (PMID 33425886, 2020). "The results showed that lectin, dorsal, wnt6, hsp70, integrin and caspase have a significant impact in M. nipponense against DIV1 infection." (PMID 39409813, 2024). "Our results showed that multiple immune-related genes (e.g., lectin, dorsal, wnt6, hsp70, integrin and caspase) may play a significant role in M. nipponense against DIV1 infection, and the immune-related signaling pathways were significantly activated." (PMID 39409813, 2024). "The results showed that a total of 7014 DEGs were expressed in the DIV1-infected group, the immune-related signaling pathways were significantly activated, and lectin, dorsal, wnt6, hsp70, integrin and caspase may have a significant role against DIV1 infection." (PMID 39409813, 2024).
infectious disease (1 paper, 2016). A disorder directly resulting from the presence and activity of a microbial, viral, or parasitic agent in humans. "Collectively, the currently available data demonstrate that Wnt6 is expressed during M. tuberculosis infection, but may also be expressed in the context of other inflammatory and infectious disease settings." (PMID 28082976, 2016). "The fact that Wnt6 is also induced by conserved microbial structures suggests that it may play a role not only during mycobacterial infections but also in the context of other infectious diseases." (PMID 28082976, 2016).
renal diseases (1 paper, 2020). "In summary, the loss of WNT6 has the potential to cause the development of renal diseases, and the expression of WNT6 induces the formation of new renal tubules, suggesting that WNT6 has regenerative and repair functions." (PMID 33425886, 2020).
WNT6 also shares sentences with these, for which no sentence is quoted: rectal cancer (2 papers); testicular germ cell tumor (2); astrocytoma (1); bacterial infections (1); brachydactyly (1); cardiovascular diseases (1); cholangiocarcinoma (1); Infertility (1); interstitial cystitis (1); lung carcinoma (1); lymphoma (1); Miscarriage (1); neuroblastoma (1); oligodendroglioma (1); ovarian carcinoma (1); schizophrenia (1); smooth muscle tumor (1); ulcerative colitis (1); viral infection (1).